KRAS (KRas proto-oncogene, GTPase)
Diseases named in the same sentence as KRAS in open-access papers (continued):
Sharing a sentence is not in itself a finding about the gene and the disease.
tumor (continued). "The aim of this study was to investigate the predictive value of haematological parameters and serum tumour markers (STMs) for KRAS gene mutations." (PMID 33183271, 2020). "In our study, two pieces of tumor tissues were available from nine patients and one discordance in the KRAS mutation was observed in one out of the nine (11%) patients (data not shown)." (PMID 32449983, 2020). "Although the rate of mutations has been shown to accumulate after chemotherapy, data specifically changes from KRAS mutation in the primary tumor to WT in the metastasis seems to be a rare event." (PMID 33002027, 2020). "All KRAS mutations detected in tumor with mucinous differentiation were within codon 12 (21 cases), 13 (3 cases), 61 (2 cases), 117 (1 case) and 146 (1 case)." (PMID 32384877, 2020). "Among these tumor types, we identified numerous significant associations between KRAS mutation and olaparib sensitivity (p < 0.002 for Colorectal and ovarian, p = 3e-6 overall." (PMID 32398776, 2020). "The rate of KRAS mutations was significantly also higher in high-grade IPNBs, and KRAS mutations were significantly associated with the tumor size and Ki-67 expression." (PMID 33317146, 2020). "Mutant forms of KRAS can cause a stable activation of those cellular pathways conferring a more aggressive tumor phenotype and resistance to anti-EGFR agents as cetuximab or panitumumab." (PMID 32625092, 2020). "Of the 96 NSCLC sample pairs analyzed, we found that 18 patients (18.75%) were positively concordant; that is, KRAS G12/G13 mutations were detected in both cfDNA by ddPCR and in tumor tissues via Sanger sequencing." (PMID 33233668, 2020). "Simultaneous KRAS mutation in both tumor and serum is associated with worse prognosis than when the mutation is only detected in tissue." (PMID 33585224, 2020). "Screening for the driving lesions BRAFV600E and N/H/KRAS mutations, and gene fusions was also performed to correlate results with tumor genotype." (PMID 31906302, 2020). "KRAS mutations in CGCG most frequently involve codon 12 which is the most frequently mutated exon of KRAS in neoplasia in general." (PMID 31838586, 2020). "Cancer cells with KRAS mutations can avoid being attacked by the immune system, facilitating immune evasion or immunosuppression phenotypes of the tumor." (PMID 33194642, 2020). "We examined KRAS mutated circulating cell-free tumor DNA (ctDNA) in CLM patients as a prognostic biomarker, independently or in combination with carcinoembryonic antigen (CEA)." (PMID 32867151, 2020). "Molecular analysis of primary tumor tissues revealed the following RAS mutations: KRAS G12D (two cases); KRAS G12V (three cases); KRAS G12C (three cases); KRAS G13D (one case); NRAS G12D (one case); NRAS A146T (one case); NRAS Q61R (one case)." (PMID 33291569, 2020). "KRAS mutated tumors had a significantly lower infiltration of NKp46+ NKT cells in the tumor and stromal compartments, and higher infiltration of NK cells, CD56+ NKT cells and CD68+ macrophages in the stromal compartment." (PMID 33013928, 2020). "All patients entering the PROSPECT trials were tested for KRAS/NRAS mutations in the archival tumor biopsy by standard COBAS methodology, as this precluded entry into PROSPECT-C study." (PMID 33014822, 2020). "The mutation of KRAS gene in tumor tissues is an independent predictor of the long‐term benefit of immunotherapy, and the predictive ability is better." (PMID 32342665, 2020).
tumor (continued). "So, in addition to Sanger sequencing and ASPCR approaches, we performed an RFLP based KRAS 12th codon mutation detection assay in another 24 PDAC tumours as well as in the validation cohort." (PMID 32552660, 2020). "Because of the low affinity of drugs for KRAS mutations, it was difficult to target these tumor genes directly." (PMID 32486141, 2020). "A recent report elucidated loss of heterozygosity (LOH) at the HLA alleles; in particular, loss of HLA-C*08:02 was observed in a resistant lesion treated with tumor-infiltrating lymphocytes composed of cytotoxic T cell clones targeting the KRAS G12D mutation." (PMID 31963413, 2020). "KRAS mutations are detectable relatively early in colon carcinogenesis, which is relevant to tumor progression and seems to be associated with distant metastases." (PMID 32258125, 2020). "KRAS is a one of the most frequently mutated oncogenes in cancer and has been shown to regulate signaling in several components of the tumor cells." (PMID 32626534, 2020). "After surgical removal of this patient’s RAS wild-type primary tumor, only a small number of KRAS-mutated subclones were found in his plasma with a mutational frequency of 0.26%." (PMID 33066758, 2020). "Mutant KRAS was associated with increases in tumor infiltrating lymphocytes, PD-L1 expression and tumor mutational burden." (PMID 32560574, 2020). "In case of the hypermutating tumor, we identified the two most common KRAS and PIK3CA activating mutations." (PMID 32873813, 2020). "We successfully amplified and detected mutant KRAS in 11 of 12 tumor samples harboring the mutation; the positive mutation frequency was as low as 0.8%." (PMID 32704002, 2020). "We confirmed a high concordance in the KRAS mutation status between the primary tumor and the metastatic lesion, which seems to maintain stable during carcinogenesis." (PMID 33002027, 2020). "Mutation of the KRAS gene is found in nearly two fifths of CRCs and is regarded as an independent prognostic factor for survival and a downstream marker of tumor resistance to anti-EGFR-targeted therapy." (PMID 33575207, 2020). "Through single-sample Gene Set Enrichment Analysis and Gene Set Enrichment Analysis, we found that KRAS mutations negatively correlated with enrichment levels of tumor infiltrating lymphocytes, inflammation, and cytolytic activities." (PMID 33254149, 2020). "Similar to previous reports, this study also identified almost 80% of all the KRAS mutation at 12thcodon among all KRAS mutations in our PDAC tumours." (PMID 32552660, 2020). "Multiple KRAS mutations were found in the tumor obtained from one patient with IPMN-associated carcinoma." (PMID 32704002, 2020). "Within these eleven studies, analysis of tumor mutational events varied from driver gene genotyping of KRAS, BRAF, and/or NRAS, to analysis of the genome-wide mutational spectrum of the tumor." (PMID 33228212, 2020). "The guidelines of the National Comprehensive Cancer Network recommend that the tumour tissues of all patients with suspected or proven metastatic CRC should undergo genotyping for KRAS mutations." (PMID 33183271, 2020). "We systematically demonstrated that gene-editing and mRNA-regulating systems specifically targeted the KRAS G12S mutant allele, which resulted in the inhibition of tumor cell proliferation and growth in vitro and in vivo." (PMID 32308773, 2020).
tumor (continued). "For example, somatic mutations of KRAS gene in tumor can cause resistance to anti-EGFR therapy, which makes it necessary to test KRAS mutation status before the therapy is given." (PMID 32590745, 2020). "The tumour mutational profile highlighted the presence of a KRAS mutation; thus, a treatment with the FOLFOX6 regimen plus bevacizumab was planned." (PMID 32899374, 2020). "In the current standard of care the presence of KRAS mutations is determined in tissue biopsies obtained from the tumour." (PMID 32415199, 2020). "Mutational analysis of the three mouse tumor lines revealed that, as expected, mutated KRAS is a key driver mutation in PDA30364." (PMID 32358491, 2020). "KRAS mutations were found more frequently in men (P < 0.001), former or current smokers (P < 0.001), and patients who had a higher level of serum tumor markers (P = 0.048)." (PMID 32729257, 2020). "Tumor site information, which was found to be significantly associated with KRAS mutation, was broadly grouped into different main organ loacation." (PMID 32628708, 2020). "Together with the compelling prevalence of its mutated form in human tumor samples, this pointed to oncogenic KRAS as the key driver of PDA carcinogenesis." (PMID 32932616, 2020). "Kirsten Rat Sarcoma Viral Oncogene Homolog (KRAS) mutations occur in approximately one-third of colorectal (CRC) tumours and have been associated with poor prognosis and resistance to some therapeutics." (PMID 32300895, 2020). "Aim of this study was to evaluate associations between metabolic parameters and KRAS status in metastatic CRC (mCRC) according to a new tumour site classification." (PMID 32594310, 2020). "KRAS mutations were observed in five primary tumors (P18, P19, P20, P24, and P39) and paired tumor-derived organoids." (PMID 32290033, 2020). "The second strategy is inhibiting the KRAS membrane association which impairs the localization of KRAS and the signal transduction of tumor proliferation." (PMID 32968059, 2020). "Studies of the association between BMI and molecular subtypes of CRC defined by key molecular tumor features such as KRAS and BRAF mutation status or MSI status have been inconclusive." (PMID 32210264, 2020). "In this study, we focused on the assessment of a potential KRAS mutation heterogeneity between the primary tumor and the corresponding recurrence site in the same patient cohort (referred to as intertumoral heterogeneity)." (PMID 33002027, 2020). "Ablation of the KRAS mutation in colon cells can lead to tumor regression in mice, suggesting its importance in colon carcinogenesis." (PMID 33254149, 2020). "This assay can detect the presence of KRAS hotspot mutations in clinical circulating tumor DNA samples." (PMID 32207862, 2020). "The KRAS mutations identified by NGS in tumor tissue were analyzed by ddPCR in matched plasma samples." (PMID 33322500, 2020). "Since the presence of the HLA-C*08:02 allele is requisite for the presentation of the neoantigen KRAS G12D and tumor recognition by T lymphocytes, its loss was supposed to directly cause immune evasion." (PMID 31963413, 2020). "The effect of KRAS mutation status was explored in the subgroup of patients for whom mutation testing of the primary tumour was available (N = 64), 30% of which were KRAS mutant." (PMID 32866563, 2020).
tumor (continued). "In comparison to LD tumours, LI tumours were significantly enriched for left-sided tumours (sigmoid and rectum), KRAS mutations and CMS2 (canonical) classification, consistent with conventional lesion molecular pathway." (PMID 31563876, 2020). "Considering that dynamic, we aimed to determine how v-raf murine sarcoma viral oncogene homolog B1 (BRAF) V600E and Kirsten rat sarcoma (KRAS) mutations relate to the location, histopathology, and degree of tumor differentiation in CRC." (PMID 33145020, 2020). "Corresponding with previous studies, in a recent KEYNOTE‐189 trial, PD‐L1 expression and TMB level of tumor tissue (tTMB) tended to be higher among patients with KRAS mutations." (PMID 33022831, 2020). "In our cohort, Case. had KRAS G12C mutation detected from the tumor tissue sample, which was replicated by the analysis of peeling cytology sample." (PMID 32351019, 2020). "KRAS mutations have been tightly linked to tumour-promoting inflammation and attributed to be a leading factor for carcinogenesis." (PMID 33116132, 2020). "In our series, all mCRC patients had been diagnosed with KRAS mutations in their primary tumor using a limited clinical NGS cancer panel." (PMID 33237900, 2020). "Although the concordance between matched ctDNA and archival tumor tissue was high for selected ‘hot-spot’ mutations (KRAS, BRAF, PIK3CA), some differences were noted between archival tumor and ctDNA." (PMID 32010431, 2020). "An in vivo Anti-Tumor effect can theoretically be achieved by directly targeting KRAS mutations through immunotherapies, as long as KRAS mutations are displayed on tumor cells." (PMID 32903495, 2020). "Transcriptome and metabolomic analyses have indicated the vital role of KRAS mutations in the control of tumor metabolism through the stimulation of glucose uptake." (PMID 32703218, 2020). "Among 96 patients with available KRAS tissue genotyping data: 35 (36.46%) carried a KRAS codon 12/13 mutation in tumor tissue and 61 (63.54%) were KRAS codon 12/13 wild-type." (PMID 33233668, 2020). "In a phase II clinical study, ganetespib was recently studied as monotherapy in previously treated NSCLC patients, and among 17 patients with KRAS mutations, 47% were reported to have tumor shrinkage." (PMID 33022831, 2020). "Two known pathogenic mutations associated also with urachal cancers; FGFR4 and KRAS and seven known mutations associated with a drug response were identified in the patient’s tumor cells." (PMID 32576176, 2020). "In conclusion, the mutation of the KRAS gene in tumor tissues is an independent predictor of the long‐term benefit of immunotherapy, with strong predictive ability." (PMID 32342665, 2020). "The median PFS was 1.64 months (95% CI = 0.46–4.37 months) for patients with plasma KRAS mutations only (pMUT-tWT) and 10.95 months (95% CI = 2.79–25.58 months) in patients with tumor tissue mutations only (pWT-tMUT)." (PMID 33233668, 2020). "To improve antigen-specific immune responses and Anti-Tumor effects on tumors expressing KRAS G12D mutation, we designed recombinant proteins containing KRAS peptide (amino acids 5–21) with G12D (called SP) in two forms: DTT-SP4 and DTSP." (PMID 32903495, 2020). "On the other hand, KRAS mutated tumours were associated with decreased fractions of CD69+ Th cells, Tregs, CD69+ NK cells and CD69+ B cells." (PMID 33228141, 2020).
tumor (continued). "The tumor with KRAS K117N also carried a FAT1 mutation present at the subclonal level in the primary tumor and later found to be enriched at time of relapse." (PMID 33384420, 2020). "KRAS mutations in tumor tissue were identified by next-generation sequencing and quantified in tumor and plasma by droplet digital polymerase chain reaction (ddPCR)." (PMID 33322500, 2020). "The LASSO, SCAD and MCP analyses all selected age, location, tumor size and stage, regional positive nodes amount, KRAS mutation status, chemotherapy experience and radiotherapy experience as the key prognostic variables of our nomogram." (PMID 32547859, 2020). "For example, arginine methylation of MDH1 induced by coactivator-associated arginine methyltransferase 1 (CARM1) suppresses tumor growth, but KRAS activation and oxidative stress relieve such inhibition." (PMID 32122374, 2020). "Across all samples from tumor patients, KRAS was the most frequently mutated gene, being mutated in 16 out of 17 PDAC patients and in both metastatic CCA patients." (PMID 33375555, 2020). "Such heterogeneity of response among patients with KRAS+ tumors mirrors the complexities of tumor biology and the presence of other aberrant driver mutations or disruption of signaling feedback loops." (PMID 32560574, 2020). "Sequencing further revealed distinct KRAS mutation in each tumor, with one tumor harboring the KRAS-G12C mutation, and the other tumor harboring the KRAS-Q61H mutation." (PMID 32415761, 2020). "KRAS mutation status of the primary tumour was collected by retrospective review of pathology reports." (PMID 32866563, 2020). "The mutation rate of RAS varies depending on tumor type, with KRAS mutations occurring in over 90% of pancreatic carcinomas and 30–50% of colorectal cancer." (PMID 30782064, 2019). "Tumor KRAS and NRAS mutational statuses are usually assessed using polymerase chain reaction (PCR)-based assays designed for detection of major hotspot mutations." (PMID 31068650, 2019). "This protein modulates cell polarization, adhesion, and migration in tumor-derived cells and is strongly associated with cancer metastasis and the expression of oncogenic factors that include KRAS, MYC, and MDR1." (PMID 31796082, 2019). "Single targeted therapy for MAPK/ERK associated pathways, such as anti-BRAF, -MEK and -KRAS, is inefficient because tumor cells can acquire resistance within a short time by activating alternative pathways." (PMID 30935067, 2019). "We chose a novel ERK1/2-selective pharmacologic inhibitor, SCH772984, which has shown cellular potency in tumor cells with BRAF, NRAS, or KRAS mutations and induces tumor regressions in xenograft models at toxicity-free doses." (PMID 31133044, 2019). "KRAS mutations were detected in 94% of the tumour samples from Group I (early recurrence) and 100% of tumour samples from Group II (late recurrence)." (PMID 30774772, 2019). "In advance of the investigation of KRAS-mutated ctDNA in plasma, KRAS assessment was performed in tumor tissues of 67 patients with PDAC using RASKET with a sensitivity of 1–5% and ddPCR with a sensitivity of 0.01–0.1%." (PMID 31891652, 2019). "According to these 2 classifications, the KRAS mutation was significantly more frequent in the PB subtype whatever the method used to classify tumours." (PMID 30837681, 2019). "Among the proteins showing increased levels of phosphorylation in the KRASG12V sample were MEK and ERK, reflecting the expected activation of the RAS/MEK/ERK pathway upon the presence of the activating G12V-mutation in KRAS in this tumor." (PMID 31805664, 2019).